CSNK2A3 (casein kinase 2 alpha 3)
Description:
Probable catalytic subunit of a constitutively active serine/threonine-protein kinase complex that phosphorylates a large number of substrates containing acidic residues C-terminal to the phosphorylated serine or threonine. Amplification-dependent oncogene; promotes cell proliferation and tumorigenesis by down-regulating expression of the tumor suppressor protein, PML. May play a role in the pathogenesis of the lung cancer development and progression.
Synonyms: CSNK2A1P
Tractability: Small molecule: a high-quality ligand is known. PROTAC: it is named in the literature on targeted protein degradation; ubiquitination databases record sites on it; a small molecule that binds it is known.
Gene: Protein-coding gene on chromosome 11 (11,351,942 to 11,353,250, reverse strand). Ensembl gene ENSG00000254598.
Subcellular location (Human Protein Atlas): Nucleoplasm; Primary cilium
Pathways (Reactome):
Cell-Cell communication: Regulation of CDH1 posttranslational processing and trafficking to plasma membrane
Gene Ontology:
Molecular function: protein binding; protein serine/threonine kinase activity; ATP binding; protein kinase activity; protein serine kinase activity
Biological process: positive regulation of cell growth; positive regulation of cell population proliferation; positive regulation of protein catabolic process; protein phosphorylation; double-strand break repair; regulation of protein catabolic process
Cellular component: cytosol
Genetic constraint (gnomAD): Loss-of-function variants: 31 observed, 37.68 expected, observed/expected ratio (o/e) 0.82, 90% interval 0.62 to 1.11. The upper end of that interval is the gene's LOEUF score, 1.11, which puts it in group 4 of 6, group 1 being the genes least tolerant of losing a copy. Missense variants: 443 observed, 499.35 expected, observed/expected ratio (o/e) 0.89, 90% interval 0.82 to 0.96. Synonymous variants: 152 observed, 179.17 expected, observed/expected ratio (o/e) 0.85, 90% interval 0.74 to 0.97.
Homologues: Orthologues: chimpanzee CSNK2A1 (98% identical), dog CSNK2A1 (98% identical), macaque CSNK2A1 (98% identical), rabbit CSNK2A1 (98% identical), mouse Csnk2a1 (97% identical), rat Csnk2a1 (97% identical), tropical clawed frog csnk2a1 (89% identical), zebrafish csnk2a4 (80% identical), Drosophila melanogaster CkIIalpha (74% identical), Caenorhabditis elegans kin-3 (72% identical). Paralogues in human: CSNK2A1 (98% identical), CSNK2A2 (74% identical).
Diseases named in the same sentence as CSNK2A3 in open-access papers:
CSNK2A3 is named in the same sentence as 9 diseases in open-access papers, as found by Europe PMC text mining. Sharing a sentence is not in itself a finding about the gene and the disease. The quoted sentences say what the papers report.
lung carcinoma (2 papers, 2010 to 2022). "Recently other studies revealed that CSNK2A3 is expressed in 293 T, A549, and NIH-3T3 cells and further polymorphism of CSNK2A3 plays oncogenic roles in lung cancer." (PMID 35123428, 2022). "Thus, the overall results indicated that OGR1 upregulates the expression of CSNK2A3 and NEP, but not CSNK2A1 in lung cancer cells." (PMID 35123428, 2022).
breast carcinoma (1 paper, 2020). "In breast cancer (BRCA), overexpression of six dark kinases is associated with decreased overall survival (ALPK3, CSNK1A1L, CSNK2A3, NRK, POMK, and PSKH1)." (PMID 33205077, 2020).
lung adenocarcinoma (1 paper, 2022). A carcinoma that arises from the lung and is characterized by the presence of malignant glandular epithelial cells. "Similar to lung adenocarcinoma, overexpression of CSNK2A3 in renal clear cell carcinoma led to increased survival." (PMID 35123428, 2022). "However, in lung adenocarcinoma, high levels of CSNK2A2 (CK2α′) and CSNK2A3 correlate with higher survival rates." (PMID 35123428, 2022).
melanoma (1 paper, 2020). A malignant, usually aggressive tumor composed of atypical, neoplastic melanocytes. "Our data showed that DAPT blockade in melanoma leads to the up-regulation of AXIN1, CSNK2A3, CEBPA2, CTNNB1, and c-myc genes in tumors." (PMID 32695658, 2020).
cancer (4 papers, 2010 to 2023). A tumor composed of atypical neoplastic, often pleomorphic cells that invade other tissues. "However, further investigation is required to find out the expression of CSNK2A1 and CSNK2A3 in various cancer cells employing strategies that can distinguish expression from one another." (PMID 35123428, 2022). "The CSNK2A3 might have an advantage over the CSNK2A1 in cancer cells in which sophisticated lineage-specific gene expression is necessary." (PMID 35123428, 2022). "CSNK2A3 might have an advantage over the CSNK2A1 in cancer cells in which sophisticated lineage-specific gene (s) expression is necessary." (PMID 35123428, 2022). "Additionally, an intronless CK2α pseudogene (CK2aP, coded by CSNK2A1P/CSNK2A3) codes for a predicted non-coding RNA that is relevant in human cancer." (PMID 29206231, 2017). "Our findings suggest that the aberrantly expressed transcript and/or protein of CK2α found in various cancer cells may be due to regulated CSNK2A3 (CK2αP) expression, which is potentially inducible or repressible by several master regulators of developmental pathways." (PMID 35123428, 2022). "Therefore, our findings suggest that the aberrantly expressed transcript and/or protein of CK2α found in various cancer cells may be due to regulated CSNK2A3/CK2αP expression, which is potentially inducible or repressible by several master regulators of developmental pathways." (PMID 35123428, 2022). "In the current study, we report for the first time the OGR1-induced regulation of CSNK2A3, CK2αP, and NEP in A549 cancer cells." (PMID 35123428, 2022).
Tumor (3 papers, 2010 to 2023). "Our data supported that the long-term and not short-term inhibition of Notch by DAPT may enhance tumor growth and motility through up-regulation of AXIN1, CSNK2A3, and CEBPA2 genes in B-raf mutated A375 cells." (PMID 32695658, 2020).
CSNK2A3 also shares sentences with these, for which no sentence is quoted: leukemia (1 paper); non-small cell lung carcinoma (1); T-cell leukemia (1).